AXL (AXL receptor tyrosine kinase)
Diseases named in the same sentence as AXL in open-access papers (continued):
Sharing a sentence is not in itself a finding about the gene and the disease.
tumor (continued). "More importantly, aberrant glycosylation of AXL was reported to contribute to tumor proliferation, invasion and metastasis, and alpha-2, 6-sialyltransferases ST6GalNAcII was further identified as critical modulator of its functions in mammary phyllodes tumors." (PMID 27015365, 2016). "We found AXL protein expression increasing during tumor progression with highest expression levels in recurrent tumors." (PMID 28025482, 2016). "Our patient-derived data and in vitro results show that, in HNSCC, AXL is important for the progression to more advanced tumor stages." (PMID 28025482, 2016). "Genetic inactivation of AXL in mesenchymal tumor cells leads to a decrease in the expression of mesenchymal markers, an increase in the expression of the epithelial marker E-cadherin, and reduced invasive potential." (PMID 27834845, 2016). "AXL was first described as a factor that promoted chemotherapy resistance in multiple tumor types including AML, non-small cell lung cancer, triple negative breast cancer, esophageal, and ovarian cancer." (PMID 27834845, 2016). "AXL is highly expressed by mesenchymal tumor cells where it plays an important role in maintaining the mesenchymal and invasive phenotype." (PMID 27834845, 2016). "Several small-molecule inhibitors of AXL are being investigated as both single agents and in combination for their anti-tumor effects in cancers with high AXL expression." (PMID 26573603, 2015). "Knockdown of AXL in Lipo-246 cells increased apoptosis and decreased cell proliferation, greatly reducing tumor volume and weight." (PMID 26573603, 2015). "It has also been reported that RNAi-mediated knockdown of AXL in pancreatic adenocarcinoma and breast and lung cancer cells decreases migration, invasion, tumor growth, and metastasis and also impairs angiogenesis." (PMID 26573603, 2015). "Treatment of cells bearing activated AXL with a humanized AXL antibody inhibited cell proliferation and migration in vitro, and tumor growth in mice." (PMID 26356563, 2015). "We performed a Western blot analysis for the expression of AXL and the activated downstream pathways in the tumours: pAXL, pAKT and pS6 ribosomal protein levels were decreased in foretinib treated mice." (PMID 25966280, 2015). "In our current analyses, AUY922 significantly reduced the invasive and migratory capabilities of both tumor cells with MET or AXL activation." (PMID 25780909, 2015). "Hypoxic conditions in the tumor increase the expression of HIF1α, which directly promotes transcription of AXL." (PMID 26328272, 2015). "Next we assessed the levels of the AXL ligand GAS6 in tumor cell-conditioned media in order to determine the potential for autocrine activation of AXL in LPS oncogenicity." (PMID 26573603, 2015). "We also demonstrate that one of the degradation mechanisms of AXL is associated with PS-RIP, and thus, enhancing the degradation of AXL can effectively inhibit cell proliferation and tumor growth in NSCLC and EGFR-TKI-resistant NSCLC cells." (PMID 25760142, 2015). "AXL and GAS6 were markedly present in less differentiated tumour specimens and only GAS6 was associated with lymph nodes status and consequently with tumour stage, showing a higher expression in more advanced disease." (PMID 25966280, 2015). "AXL knockdown in Lipo-246 and Lipo-863 cells significantly reduced tumor volume (p < 0.001) compared with that for NT control xenografts (respectively)." (PMID 26573603, 2015). "AXL protein expression by immunohistochemistry (IHC) was detected in 171 out of 223 tumour specimens (76.7%) whereas AXL expression was undetectable in 52 out of 223 (23.3%)." (PMID 25966280, 2015). "AXL has a well established oncogenic role in survival, proliferation and migration of cancer cells in vitro, as well as in tumor angiogenesis and metastasis in vivo." (PMID 25193853, 2014).
tumor (continued). "Because samples with highest AXL expression (score 3) seemed to be a distinct group and to increase statistical power for survival analysis, the primary tumor cohort was divided into two groups: low (scores 0–2) and high (score 3) AXL expression." (PMID 25528764, 2014). "Herein, we set out to investigate the feasibility using soluble AXL as a marker to assess NF1 related tumor burden." (PMID 25551830, 2014). "Immunopositivity (defined as intensity score > 0) for AXL was detected in the majority of specimens (n = 26; 72%) and virtually all positive sections demonstrated protein expression in > 70% of tumor cells." (PMID 25528764, 2014). "Therapeutic AXL antibodies are also in development with promising in vitro and in vivo results in several tumor types." (PMID 25528764, 2014). "In one study sAXL was detected in the tumor exudates of xenograft mice; however, the authors used an antibody that detected both murine and human AXL." (PMID 25551830, 2014). "In conclusion, we report an increased expression and phosphorylation of AXL in MPNST cells with a corresponding increase in levels of sAXL in the medium when the tumor cells were grown in culture and in the mouse plasma when injected into nude mice." (PMID 25551830, 2014). "In particular, 12 genes, including AXL, CDH1, CFLAR, FKBP1A, NT5E, and VIM, were reported to be significantly associated with tumor metastasis (P<8E-04)." (PMID 23185353, 2012). "AXL is activated in tumor cells by growth arrest specific gene 6 (Gas6), a soluble serum protein, in an autocrine fashion." (PMID 23077658, 2012). "This was the first direct proof that the tyrosine kinase activity of AXL can be involved in tumor progression." (PMID 22141136, 2011). "This can be exemplified by the Gas6/AXL system where the addition of antibodies against the protein Gas 6 potentiated the inhibition elicited by the NPC on the N29 tumor and to a lesser extent on N32." (PMID 19558675, 2009). "Some have been shown previously to be of importance for tumor growth, invasion, metastasis and/or chemotaxis, such as Gas6/AXL and CXCL1." (PMID 19558675, 2009). "The Gas6/AXL pathway has also been shown to protect epithelial/endothelial cells from apoptosis and has been suggested to play an important role in tumor vascularization." (PMID 19558675, 2009). "This was further strengthened by the fact that addition of antibodies against the Gas6 receptor AXL also increased the inhibition of tumor proliferation on N29 and N32 using HiB5." (PMID 19558675, 2009). "Interestingly, again significantly lower AXL serum values were found in the tumor patients compared to healthy controls." (PMID 41563267, 2026). "Moreover, ZAXL:239 was found to have significant anti-tumor effects in AXL-positive GC transplantation tumor nude mouse models." (PMID 39644434, 2025). "Mechanistic investigations revealed that ABCB5 promotes the ability of tumor cells to infiltrate into the blood vessels, which may be regulated by IL-8/AXL signaling." (PMID 40746888, 2025). "Furthermore, the AXL/MERTK signaling blockade sensitized tumor cells to anti–programmed cell death 1 (anti–PD-1) treatment." (PMID 39774471, 2025). "Therefore, AXL has emerged as a promising tumor target antigen for the development of CAR-T-cell therapy, which has demonstrated encouraging preclinical therapeutic results." (PMID 40299452, 2025). "We found intensive reciprocal interactions between TICs and immune-regulatory tumor-associated macrophages (Reg-TAMs) via growth arrest–specific 6/AXL receptor tyrosine kinase/MER proto-oncogene, tyrosine kinase (GAS6/AXL/MERTK) signaling pathways, which facilitated the immune escape of TICs." (PMID 39774471, 2025). "When AXL is turned on, tumour cells make immune checkpoint molecules." (PMID 40088262, 2025).
tumor (continued). "However, despite AXL being a DEG in MES-dominant tumor samples and cell line models, here we show that it is neither necessary for MES subtype maintenance nor sufficient to transdifferentiate ADRN cells to a MES-like phenotype." (PMID 39825754, 2025). "The results indicated that AXL was significantly overexpressed in ccRCC tumor tissues." (PMID 41029360, 2025). "Finally, we discuss the translational relevance of AXL-targeted therapies in enhancing the patient outcomes by reducing resistance and promoting tumor regression." (PMID 39924521, 2025). "Targeted therapies, though effective in suppressing specific oncogenic pathways, frequently induce compensatory signaling cascades such as the c-Mesenchymal-Epithelial Transition factor (MET) or AXL Receptor Tyrosine Kinase (AXL) upregulation, enabling tumor escape mechanisms." (PMID 40428998, 2025). "This evidence suggests that AXL also plays a role in tumor immunity." (PMID 40959280, 2025). "Combined RNAscope and immunofluorescence for CDH2, AXL, FAK, PD-L1, and miR-210, integrated with spatial transcriptomics, could map hybrid E/M niches and EV-linked immune states across tumor stages." (PMID 41462674, 2025). "In addition, another study revealed that ABCB5 promotes tumor vascular invasion and metastasis by activating IL-8/AXL signaling." (PMID 40746888, 2025). "Furthermore, immunohistochemistry (IHC) scores > 2 for both c-MET and AXL were observed in 70% and 90% of tumor specimens, respectively." (PMID 40921965, 2025). "AXL regulates the immune responses of NK cells and cytotoxic T cells (CTLs) in human tumours." (PMID 40088262, 2025). "Our findings underscore the significance of c-MET and AXL as major tumor growth pathways in CDC." (PMID 40921965, 2025). "Similarly, AXL inhibitors, such as bemcentinib, are being explored for their role in targeting mesenchymal-like tumor cells that are resistant to conventional therapy." (PMID 40277909, 2025). "TAMs and cancer-associated fibroblasts (CAFs) may drive immune suppression and tumor growth via AXL signaling." (PMID 40575267, 2025). "We found that WNT-activated malignant epithelial cells interacted intensively with immune-regulatory tumor-associated macrophages (Reg-TAMs) via the growth arrest–specific 6/AXL receptor tyrosine kinase/MER proto-oncogene, tyrosine kinase (GAS6/AXL/MERTK) pathway." (PMID 39774471, 2025). "Furthermore, large cytotoxic effects were observed in vitro and decreased tumor size in MDA-MB-231-derived xenograft mouse models using a novel combination strategy that combined constitutive active IL-7 receptor inhibition with AXL-CAR-T." (PMID 39755633, 2025). "Beyond its role in tumor-intrinsic biology, AXL also influences the tumor microenvironment." (PMID 41009462, 2025). "Notably, MET and AXL (both known to be involved in the survival, proliferation, infiltration, and metastasis of tumor cells as well as in the mechanisms of tumor resistance to molecularly targeted agents) were reported to be overexpressed in RCC." (PMID 38289361, 2024). "Additionally, they substantiated the conclusion that the metformin-induced suppression of tumor growth in vivo is highly contingent on AXL expression, as demonstrated in a tumor xenograft mouse model of EAC." (PMID 38474224, 2024). "AXL is a receptor tyrosine kinase, and its overexpression contributes to tumor malignancy." (PMID 39660536, 2024). "In some cancers, AXL appears to promote the immunosuppressive tumor microenvironment." (PMID 39598377, 2024). "AXL and Rho A activate the β-catenin pathway, enhancing metastasis and tumor progression." (PMID 39590305, 2024). "In GC, AXL plays a pivotal role in promoting tumor growth, invasion, and metastasis." (PMID 39597836, 2024). "Pharmacological targeting of AXL in combination with TKI could evoke a more immunogenic phenotype of the tumor and potentiate the treatment efficacy of subsequent immunotherapy in TKI-resistant HCC." (PMID 38310091, 2024).
tumor (continued). "However, recent studies have provided evidence that PROS1 can also activate AXL in tumor cells, thereby promoting tumor cell proliferation and invasiveness." (PMID 38254761, 2024). "The primary endpoint was that AXL expression on tumor and immune cells was associated with a negative impact on ICI prognosis." (PMID 39238637, 2024). "Interestingly, the anti-tumor effect of sdAb20-Fc clearly correlated with the AXL-positivity within the blasts." (PMID 38773967, 2024). "In addition to direct effects on tumor cells, AXL and cannabinoids have been reported to regulate the immune cells." (PMID 39598377, 2024). "Tumor-cell AXL expression correlated with aggressive phenotypic features including reduced OS in patients treated with ICIs (P = 0.04) after chemotherapy progression, but conversely associated with improved disease control (P = 0.045) in ICI-treated, PD-L1 high first-line patients." (PMID 39238637, 2024). "Overall, this study suggests that more differentiated MITF+ tumors are efficiently targeted by immunotherapy, while AXL+ tumor cells may be more resistant, analogous to their response to targeted therapy." (PMID 39697983, 2024). "Based on previous findings that combination targeting of S6K1 and AXL effectively reduced viability of PTEN-deficient GBM, we initiated preclinical therapeutic studies by testing inhibitor effects on tumor growth in nude mice that were injected subcutaneously with PTEN-deficient GBM U87MG." (PMID 39087397, 2024). "Surprisingly, we found differences in the predictive value of tumor- versus immune-AXL expression." (PMID 39238637, 2024). "AXL is both expressed by tumor and a variety of stromal cells, including CAFs." (PMID 39697983, 2024). "Collectively, these findings strongly suggest that AXL may contribute to emergence of osimertinib‐tolerant tumor cells which were observed in surgical specimens obtained from two patients." (PMID 38323355, 2024). "Tumor samples from 111 NSCLC patients treated with ICI monotherapy in first line (1L) or after one-or-more lines of chemotherapy (2L) were evaluated for AXL expression by immunohistochemistry (IHC)." (PMID 39238637, 2024). "Therefore, it is meaningful to evaluate the synergistic anti-tumor effect of AXL inhibition with WIN55212-2 in vitro and in vivo, and uncover its underlying mechanism." (PMID 39598377, 2024). "We detected weak AXL expression in tumor cells at initial biopsy in both patients." (PMID 38323355, 2024). "Moreover, besides its clear single agent anti-tumor effect, our data also demonstrated the therapeutic potential of AXL-specific sdAb20-Fc in combination with the standard-of-care agent cytarabine, which resulted in a synergistic effect." (PMID 38773967, 2024). "To further validate the involvement of the PROS1-AXL axis in the upregulation of macrophage MMP9 via MICA+ tumor cells, we introduced the AXL inhibitor cabozantinib to macrophages stimulated via recombinant human PROS1 protein and co-cultured with IRF1+ Huh7 cells." (PMID 38254761, 2024). "The microenvironment of KIC tumors lacking AXL is more inflammatory, with increased infiltration of T and NK cells and a significant drop in tumor-associated macrophages." (PMID 38391974, 2024). "Furthermore, OS-low patients had higher AXL expression in tumor cells, providing orthogonal evidence of the poor ICI-prognostic effect of tAXL expression at the single-cell IMC level." (PMID 39238637, 2024). "Additionally, we will explore the potential of AXL as a therapeutic target to overcome tumor chemoresistance." (PMID 37328828, 2023). "In CRC cell lines, treatment with the TGFβ inhibitor, galunisertib, and the AXL inhibitor, R428, markedly reduced colony formation and migration of cancer cells, and demonstrated potent anti-tumor activity in 3D spheroid cultures obtained from individuals with advanced CRC." (PMID 37469409, 2023).
tumor (continued). "Furthermore, emerging findings indicate a key role of AXL in immunosuppressive tumor-microenvironment remodeling and in enhancing immune escape, including MHC-I down-regulation and induction of PD-1/PDL-1 expression." (PMID 37143061, 2023). "AXL is in fact differentially expressed among cancer and healthy tissues and its overexpression correlates with worse prognosis in several tumor types, wherein it plays a crucial role in cell growth and migration, in epithelial-mesenchymal transition (EMT), and chemoresistance." (PMID 37143061, 2023). "Notably, MDK/LRP1, MDK/ALK, GAS6/MERTK, and GAS6/AXL between fibroblasts and tumor cells exhibited a higher communication possibility than that between fibroblasts and thyrocytes." (PMID 37733241, 2023). "Other researchers generated AXL-redirected CAR-Ts with a constitutively activated IL-7 receptor (C7R); they demonstrated a significant tumor cell killing capacity, which was more efficacious than by using conventional AXL-redirected CAR-Ts, in TNBC MDA-MB-231 and MDA-MB-468 cell lines." (PMID 36900394, 2023). "In addition, in vivo studies using subcutaneous and orthotopic intrahepatic models demonstrated that genetic inhibition of AXL resulted in tumor-growth delay." (PMID 36980768, 2023). "Thus, it was of interest that our recent discovery demonstrated that STK11 mutant NSCLCs treated with AXL inhibitors (targeting AXL in the tumor microenvironment dendritic cells) can now respond to immune checkpoint blockade therapy." (PMID 37035141, 2023). "Previous reports have suggested that AXL inhibition reduces tumor growth depending on cell types." (PMID 36980768, 2023). "The GAS6/AXL axis regulates many tumor immune-related biomolecules, e.g., major histocompatibility complex I (MHC-I) and programmed death ligand-1 (PD-L1) in tumor cells, and the levels of secreted anti-inflammatory cytokines such as IL-4, CCL3-5 and granulocyte colony-stimulating factor (G-CSF)." (PMID 37265798, 2023). "We also demonstrated that targeting AXL inhibits tumor progression." (PMID 36980768, 2023). "Additionally, tumor-related macrophages secrete 14–3-3ζ, which interacts and phosphorylates AXL to activate downstream pathways to promote the tolerance of PDAC cells to chemotherapy." (PMID 37328828, 2023). "AXL is, therefore, an attractive tumor target for immune-therapeutic strategies." (PMID 37143061, 2023). "The underlying mechanisms for these effects are still unclear, but targeting of AXL which promotes tumor immune evasion and therefore has been discussed to play a role in PD-1 resistance, might be one possible explanation." (PMID 37740836, 2023). "The receptor tyrosine kinase (RTK) AXL may be a potential mediator of T-cell rejection, increasing tumor cell invasion and metastasis and suppressing the immune response by enhancing T-cell rejection." (PMID 37265798, 2023). "Growth arrest-specific protein 6 (GAS6) is a secreted vitamin K-dependent protein that binds to the receptor AXL and promotes tumor neovascularization by regulating endothelial cell function, the activation status of integral proteins, and the expression of pro-angiogenic factors." (PMID 36816799, 2023). "GAS6/AXL was involved in promoting tumour cells’ proliferation, survival, and angiogenesis." (PMID 36813833, 2023). "Similarly to sunitinib, cabozantinib inhibits the tyrosine kinase enzymatic activities of multiple receptors including VEGFR2, MET, AXL, and RET, which have been implicated in tumor proliferation, survival and neoangiogenesis." (PMID 37752423, 2023). "In addition, the potential of AXL inhibitors in combination with other anti-tumor therapies (especially checkpoint inhibition) has also received increasing attention." (PMID 37265798, 2023).